PAX6 (paired box 6)
Diseases named in the same sentence as PAX6 in open-access papers (continued):
Sharing a sentence is not in itself a finding about the gene and the disease.
breast cancer (29 papers, 2009 to 2025). A primary or metastatic malignant neoplasm involving the breast. "For instance, PAX6 expression has been associated with proliferation and cell cycle progression of colorectal cancer cells, non-small cell lung carcinoma cells and breast cancer cells." (PMID 28700649, 2017). "PAX6 has also been implicated in promoting the proliferation of breast cancer cells, and we have reported that PAX6 is a direct MYB target gene in the neurogenic zones of the brain." (PMID 24283570, 2013). "Epigenetic inactivation of PAX6 gene was liable for progression of breast cancer, but loss this gene might be culpable for progression of pituitary prolactinoma." (PMID 33709028, 2021). "Up-regulation of PAX6 in aggressive breast cancer cells promotes migration and expression of MMP2 and MMP9 proteins, by directly binding their genes and thus activating their expression." (PMID 40506992, 2025). "Breast cancer cells knocked down for PAX6 arrest in the G0/G1-phase of the cell cycle and are unable to promote tumor growth." (PMID 40506992, 2025). "The different regulatory mechanism of PAX6 involving DANCR implies its modulation of miR-758-3p, allowing PAX6 expression and leading to a reduction in both apoptosis and autophagy in breast cancer cells." (PMID 40506992, 2025). "Methylation status of the Pax6 gene seems to be also affected by the breast cancer molecular feature." (PMID 40506992, 2025). "Another study has confirmed that miR-375 actually repress the viability, migration, and invasion of MCF-7 breast cancer cell lines by targeting the expression of PAX6." (PMID 38326829, 2024). "The ARlncRNA DANCR/miR-758/3p-PAX6 axis can inhibit autophagy and apoptosis in mammary cancer cells." (PMID 37588204, 2024). "The previously published data have also shown that cymarin inhibits MCF-7 cell proliferation by affecting PAX6 expression, making it a promising candidate for breast cancer treatment." (PMID 39683912, 2024). "In this study, we report that TNFRSF9 regulates the cell proliferation, invasion, and apoptosis of breast cancer cells through regulating the phosphorylation of p38, thus further regulating the expression of PAX6." (PMID 35799609, 2022). "In this study, we reveal that, through upregulating TNFRSF9 in breast cancer, the PAX6 expression can be downregulated through inhibiting p38 phosphorylation and preventing tumor growth." (PMID 35799609, 2022). "The study showed methylation of PAX6 was closely related to LNM in breast cancer, esophageal squamous cell carcinoma and gastric cancer." (PMID 36454866, 2022). "In summary, this study proposed a novel TNFRSF9/p38/PAX6 axis that contributes to tumor suppression, which suggests a potential immunotherapy target for breast cancer." (PMID 35799609, 2022). "In the lymph node metastasis status of breast cancer, PAX6 is switched from methylated to methylation status in the progression of metastasis, which suggests novel biomarkers for breast cancer metastasis." (PMID 35799609, 2022). "Methylation of PAX6, GSTP1, RASGRF2, and AKR1B1 promoters has been previously reported to be associated with lymph node metastasis of breast cancer." (PMID 36454866, 2022). "We further elucidate that p-p38 is essential for PAX6 expression as p38 phosphorylation inhibitor can reverse the upregulation of PAX6 and suppress cell proliferation and invasion and promote apoptosis in breast cancer cells." (PMID 35799609, 2022). "PAX6 inhibits the viability, migration, and invasion of human breast cancer MCF-7 cells, whereas CADM1 inhibits insulin secretion in INS-1 cells and primary cells." (PMID 33897780, 2021). "Methylation is involved in the development of female breast cancer, with frequent methylation of PAX6, BRCA2, PAX5, WT1, CDH13 and MSH6 in ductal carcinoma in situ and invasive ductal cancer." (PMID 22765268, 2012). "Separate studies have reported silencing of Pax6 by methyl-CpG-binding proteins in some breast cancer cell lines and primary tumours." (PMID 19703295, 2009).
breast cancer (continued). "Regarding breast cancer progression, PAX6 also exhibits a dual mode of action." (PMID 40506992, 2025). "Moreover, it is interesting to observe that the knockdown of PAX6 can remarkably inhibit cell viability, DNA synthesis and colony formation in breast cancer cell line and tumorigenesis in xenograft nude mice." (PMID 36255267, 2022). "In this study, we confirmed that downregulation of PAX6 expression could suppress breast cancer development in vivo and inhibit tumorigenesis in xenograft nude mice." (PMID 35799609, 2022). "Indeed, in breast cancer cells, PAX6 expression may be favored by a long non-coding RNA named DANCR." (PMID 40506992, 2025). "Treatment with breast cancer cell derived-exosomes, brain organoids exhibited enhanced expression of stemness-related marker OCT4 and forebrain marker PAX6." (PMID 35254502, 2022). "AKR1B1, RASGRF2, CRMP1, BNIP3, GSTP1, HOXA5 and PAX6 genes were methylated in ER-positive and HER2-negative breast cancer with ALNM." (PMID 36454866, 2022). "It has been reported that PAX6 networked with the LncRNA DANCR and played a key regulatory role in apoptosis and autophagy of breast cancer cells." (PMID 34738870, 2021). "Some established oncogenes are also direct targets of miR-655 in other types of cancers, such as Prrx1 in breast cancer, ZEB1 and TGFBR2 in ESCC, ADAM10 in hepatocellular carcinoma, and PAX6 in retinoblastoma." (PMID 33643926, 2021). "This revealed a number of significant hotspots of epigenetic deregulation, centred around important breast cancer genes, including FOXA2, PAX6 and L1CAM, with the two largest modules mapping to the WNT and FGF signalling pathways, respectively." (PMID 26823093, 2016). "Direct bisulfite sequencing also showed widespread methylation occurring in intragenic regions of the WT1, PAX6 and ITGA4 genes and in the promoter region of the OTX2 gene in breast cancer tissues." (PMID 26121976, 2015). "On the other hand, the high frequency of methylation in MSH6, PAX5, PAX6 and CDH13 was shared between male and female breast cancer." (PMID 22765268, 2012). "The most frequently hypermethylated genes (MSH6, CDH13, PAX5, PAX6 and WT1) were similar for male and female breast cancer." (PMID 22765268, 2012). "Most of these conserved TFBSs involved in breast cancer (e.g., AP-1, NFκB, and STAT5), stem cells and embryonic development (e.g., OCT1, PAX6, GATA1), and therefore had the highest potential for regulating CD44 and for being involved in breast cancer." (PMID 23226410, 2012). "These included genes/loci previously reported to be methylated in breast cancer (for example SIM1, PAX6, DLX4, RUNX3)." (PMID 20205715, 2010). "Furthermore, in addition to highly methylated AKR1B1, RASGRF2 and CRMP1 gene promoters, BNIP3, GSTP1, HOXA5 and PAX6 gene promoters were also methylated in ER-positive and HER2-negative breast cancer with ALNM." (PMID 36454866, 2022). "Targeted bisulfite sequencing showed that the promoter methylation levels of AKR1B1, BNIP3, CRMP1, GSTP1, HOXA5, PAX6, and RASGRF2 were increased in ER-positive and HER2-negative breast cancers with ALNM, compared with ER-positive and HER2-negative breast cancers without ALNM." (PMID 36454866, 2022). "Moreover, in addition to highly methylated AKR1B1, RASGRF2 and CRMP1 gene promoters, BNIP3, GSTP1, HOXA5 and PAX6 gene promoters were also methylated in ER-positive and HER2-negative breast cancer with ALNM." (PMID 36454866, 2022). "It is highly likely that a similar axis exists in breast cancer cells between TNFRSF9 and p38 or p38 and PAX6, which could be further investigated in the future." (PMID 35799609, 2022). "Additionally, Kaplan-Meier plot showed breast cancer patients with lower PAX5 expression live shorter than those with higher, while the survival rate of patients with higher PAX6 expression decreased compared to those with lower expression." (PMID 32693820, 2020).
breast cancer (continued). "Interestingly, genes with frequent methylation in male breast cancer (MSH6, CDH13, PAX5, PAX6 and WT1) were also very commonly methylated in female breast cancer." (PMID 22765268, 2012). "Indeed, a higher level of methylation within Pax6 promoter was found in ER/PR positive breast cancers compared to ER/PR negative one." (PMID 40506992, 2025). "Furthermore, in addition to highly methylated AKR1B1, RASGRF2 and CRMP1 gene promoters, BNIP3, GSTP1, HOXA5 and PAX6 gene promoters were also methylated in ER-positive and HER2-negative breast cancer with ALNM, which may serve as candidate methylation biomarkers." (PMID 36454866, 2022). "It revealed breast cancer derived exosomes might lead to the impairment of neurodevelopment in brain organoids, including increased stemness-related marker OCT4 of stem cell and forebrain marker PAX6 which were related to tumor progression and oncogenic features." (PMID 35254502, 2022). "And compared with ER-positive and HER2-negative breast cancers without ALNM, the methylation levels of AKR1B1, RASGRF2, CRMP1, BNIP3, GSTP1, HOXA5, and PAX6 promoter were increased in ER-positive and HER2-negative breast cancers with ALNM." (PMID 36454866, 2022).
coloboma (27 papers, 2007 to 2025). An abnormality in which a part of a structure in one or both eyes is missing. "The 681 kb large deletion of chromosome 11p13 downstream of PAX6 is the genetic cause of the familial ocular coloboma in this large Chinese family." (PMID 24349436, 2013). "In this study, the ocular coloboma in the large Chinese family was caused by a large deletion in the PAX6 3’ region." (PMID 24349436, 2013). "PAX6 is located on chromosome 11p13 acts as transcriptional regulator of other genes that are associated with coloboma." (PMID 21655361, 2011). "Therefore, a mutation in the PAX6 gene can lead to various pathologies such as aniridia, peters anomaly, coloboma, microphthalmia, and WAGR (Wilms tumor, aniridia, genitourinary anomalies, and (mental) retardation) syndrome." (PMID 39149643, 2024). "Patients with a PAX6 mutation occurring at the donor splice site of intron 4 have been reported to have congenital nystagmus with anterior segment anomalies (mainly iris hypoplasia or coloboma) associated with foveal hypoplasia." (PMID 32111086, 2020). "Cyp1b1 regulated the expression of vsx2, pax6, and shh, genes clinically associated with colobomas." (PMID 28192799, 2017). "However, our findings firstly discovered deletion downstream of PAX6 gene was associated with ocular coloboma." (PMID 24349436, 2013). "Ocular co-expression of TRPM3 and miR-204 is upregulated by the paired box 6 transcription factor (PAX6) and mutations in all three corresponding genes underlie inherited forms of eye disease in humans including early-onset cataract, retinal dystrophy, and coloboma." (PMID 32070426, 2020). "This is a spontaneous deletion of the Pax6 gene and heterozygous mutant mice have characteristic small eyes, which is accompanied by coloboma, lens defects, abnormal folding of the retina, reduced pigment layer, and an overall small body size." (PMID 30290306, 2018). "Heterozygous mutations in the paired box gene 6 (PAX6, OMIM 607108), located on 11p13, were previously implicated in familial and sporadic ocular coloboma even aniridia (OMIM 106210)." (PMID 24349436, 2013). "So there is still a possibility for PAX6 to be involved in coloboma cases which can be detected by CGH array." (PMID 21655361, 2011). "One possible explanation for the development of colobomas is that the decreased level of Rybp in the mutant retinas influences the normal distribution of regulatory proteins such as Pax6 or Pax2." (PMID 17470285, 2007). "In eye genetic disorders (Microphtalmia/Anophtalmia/ Coloboma-Optic Nerve Hypoplasia, MAC-ONH), only between 40 and 50% of cases are explained by mutations within the exomes of several genes, including SOX2, OTX2 and PAX6 among the most frequently mutated." (PMID 35887306, 2022). "The most common form of ocular coloboma resulting from PAX6 defects is that affecting the iris, which have been identified in patients with both nonsense, missense, and frameshift changes in PAX6, as well as the deletion of 3’regulatory region." (PMID 31861090, 2019). "We found that depletion of kdm5c significantly downregulated vax1, vax2, pax6 expressions, while tbx5 expression was slightly reduced; thus, the reduced expression of DV-patterning markers may be responsible for the colobomas observed in kdm5c morphants." (PMID 30522514, 2018). "aCGH should be applied if there is a negative result for the mutation detection of PAX6 in patients with ocular coloboma." (PMID 24349436, 2013). "However, the absence of PAX6 mutations in selected population do not rule out the possibility of involvement of this gene in coloboma." (PMID 21655361, 2011).
coloboma (continued). "The 681 kb deletion downstream of the PAX6 gene including the DCDC5, DCDC1, DNAJC24, IMMP1L genes and a part of the ELP4 gene has been discovered in a patient with ocular coloboma." (PMID 29460221, 2018). "The MAC study failed to reveal any pathogenic mutations in PAX6, CHX10, and SIX3 in patients with coloboma fundus." (PMID 33746210, 2021).
retinoblastoma (26 papers, 2006 to 2025). A malignant tumor that originates in the nuclear layer of the retina. "First, we transfected 2 retinoblastoma cell lines with a lentiviral pGCL-GFP vector encoding a PAX6 siRNA sequence." (PMID 24939714, 2014). "PAX6, which is associated with drug response, is strongly activated by cotylenin A in retinoblastoma cell lines." (PMID 22590536, 2012). "CN-A-induced PAX6 splice variant mRNA expression patterns also differed between the two retinoblastoma cell lines, corresponding to activation of three PAX6 promoters by CN-A." (PMID 20577596, 2010). "We have hypothesized that the absence tumor formation in Pax6 TKO is due to loss of Pax6 preventing the formation of the retinal subtype that gives rise to retinoblastoma." (PMID 25338120, 2014). "For instance, FEZF1-AS1 promoted growth and inhibited apoptosis by regulating miR-363-3p and PAX6 in retinoblastoma." (PMID 41331461, 2025). "Studies have shown that suppressing PAX6 expression increases cell proliferation, decreases apoptosis, and regulates cell cycle arrest in human retinoblastoma and corneal epithelial cells." (PMID 38132359, 2023). "The mechanism of action of PAX6 as a tumor suppressor has been shown in retinoblastoma, prostate cancer, and glioblastoma cell lines." (PMID 36313570, 2022). "On the other hand, some oncogenic properties of PAX6 were found in colorectal adenocarcinoma, retinoblastoma, and breast tumor cell lines." (PMID 36313570, 2022). "Our study found that ZFPM2-AS1 and PAX6 were upregulated, whereas miR-511-3p was downregulated in retinoblastoma." (PMID 34989314, 2022). "The data implied that FEZF1-AS1 regulated cell progression in retinoblastoma via miR-363-3p/PAX6, which provides a candidate therapeutic target for retinoblastoma." (PMID 33432525, 2021). "FEZF1-AS1 promoted growth and inhibited apoptosis by regulating miR-363-3p and PAX6 in retinoblastoma." (PMID 33432525, 2021). "In conclusion, FEZF1-AS1 elevated growth and inhibited apoptosis by regulating miR-363-3p/PAX6 in retinoblastoma, which provide a new target for retinoblastoma treatment." (PMID 33432525, 2021). "In particular, it has been shown that approximately 15% of sporadic retinoblastoma cases are caused by postzygotic RB1 mutations, that intrafamilial phenotypic variability in aniridia cases can be explained by PAX6 mosaicism." (PMID 33420188, 2021). "A recent study showed that microRNA MiR-433 inhibits retinoblastoma growth by suppressing Notch1 and PAX6 expression." (PMID 27661116, 2016). "Retinoblastomas arising in Chx10-Cre; Rblox/-; p107−/−; p53lox/- mice express PAX6 and Syntaxin which are markers expressed in progenitor & amacrine cells, and PKCα which is expressed in differentiated bipolar cells." (PMID 25907958, 2015). "The protein levels of PAX6 in the SO-Rb50 and Y79 retinoblastoma cell lines were significantly lower in the knockdown groups than in the control groups." (PMID 24939714, 2014). "We have previously demonstrated that the overexpression of PAX6 regulates the growth and apoptosis of human retinoblastoma cells." (PMID 24939714, 2014). "But PAX6 plays an oncogenic role in pancreatic cancer and retinoblastoma.In pancreatic adenocarcinoma and pancreatic cancer cell lines, down-regulation of PAX6 by specific siRNA leads to a decline in cell growth and cell apoptosis." (PMID 24454925, 2014).